CBX7 (chromobox 7)
Diseases named in the same sentence as CBX7 in open-access papers (continued):
Sharing a sentence is not in itself a finding about the gene and the disease.
tumor (continued). "The tumor-suppressing role of CBX7 has also recently been shown in Cbx7 knockout mice." (PMID 27449098, 2016). "However, in several human carcinomas CBX7 acts as a tumor suppressor gene preventing the acquisition of a malignant phenotype." (PMID 25595895, 2015). "In fact, CBX7 resulted progressively down-regulated in a wide array of human carcinomas including thyroid, colon, breast, pancreas and lung carcinomas in relation to tumor grade and malignant stage." (PMID 25595895, 2015). "CBX7 is a Polycomb protein that has shown tumor suppressive function and is a component of PRC1." (PMID 25881303, 2015). "Since we have previously shown that HMGA1 is able to negatively regulate CBX7 expression and that HMGA1 positively regulates miR-181 that has CBX7 as target, we can envisage a HMGA1-CBX7 network that operates in the regulation of tumour progression and adipocyte cell growth and differentiation." (PMID 25190058, 2014). "Indeed, PcG proteins EZH2, BMI1 and CBX7 have been shown to possess oncogenic or tumor suppressor functions in different tumors including GBMs." (PMID 24260522, 2013). "Thus, we hypothesize that factors secreted by the tumor microenvironment may be responsible for the regulation of CBX7 expression and function." (PMID 38037081, 2023). "CBX6 may contribute to a poor prognosis in patients by inhibiting M1 polarization and promoting Treg recruitment in the tumor microenvironment, while CBX7 may contribute to a better prognosis in patients by increasing resting mast cell numbers and decreasing macrophage M0 content." (PMID 37189494, 2023). "We speculated that CBX7 may also serve as a tumor suppressor in LUAD and LUSC." (PMID 35646140, 2022). "Also, CBX7 upregulation correlates with a better survival of tumor patients." (PMID 36361869, 2022). "Therefore, we have further focused on CBX3 and CBX7 proteins, as their association with cancer stemness is most prominent and universal regardless of the tumor type." (PMID 36361869, 2022). "Therefore, the role of CBX7 in modulating cancer stemness might be affected by the tumor origin and the prevalence of distinct interacting proteins and should be considered in a tumor-specific manner." (PMID 36361869, 2022). "On the other hand, CBX7-associated transcriptome profiles are significantly depleted with the targets for c-Myc or E2F transcription factors, as well as the markers of mTOR signaling or G2/M checkpoint, regardless of the tumor type." (PMID 36361869, 2022). "We postulated that our low-proliferative miR-181 KO liver tumours may resemble the ppHCC subtype, as miR-181ab1 KO tumours showed increased expression of some genes, such as CBX7 and FOXP2, which were mainly expressed in periportal hepatocytes (periportal genes)." (PMID 35867177, 2022). "Thus, we examined whether increased stable expression of CBX7 by rAAV with piggyBac transposase-mediated somatic integration in established primary WT tumour cells could inhibit tumour progression in vivo." (PMID 35867177, 2022). "Using the GSCA platform, we observed that across 4 tested tumor types (1641 profiled samples), the frequencies of single nucleotide variations (SNV) in CBX encoding genes were relatively low and ranged from 0.61% to 1.46% of all tested samples for CBX7 and CBX4, respectively." (PMID 36361869, 2022). "In previous studies, low CBX7 expression may be involved in promoting the tumor metastasis, in which CBX7 binds to the histone deacetylase 2 and inhibits its activity, leading to the histone deacetylation in the E-cad promoter and finally increasing the E-cad expression." (PMID 33748425, 2021). "Whether CBX7 is an oncogene or a tumor suppressor still remains controversial." (PMID 31211140, 2019). "However, the precise role of CBX7 in tumor progression is still controversial." (PMID 28460453, 2017). "However, the precise role of CBX7 in tumorigenesis and tumor progression is still controversial." (PMID 28460453, 2017).
tumor (continued). "Finally, CBX7 attenuated tumor growth in a xenografted model." (PMID 28460453, 2017). "However, other publications propose CBX7 as a potential tumor suppressor." (PMID 28030829, 2017). "However, the role of Cbx7 in human malignancies still remains ambiguous, owing to the fact that there are reports which portray Cbx7 as an oncogene as well as some of them depict its role as a tumour suppressor." (PMID 27291091, 2016). "Understanding the functional significance of the reciprocal expression pattern of CBX8 relative to CBX6 and CBX7 in GBMs might eventually leads to the development of compounds targeting the chromodomain of a specific CBX protein which potentially have anti-tumor efficacy." (PMID 24260522, 2013). "However, several recent publications propose CBX7 as a potential tumor suppressor." (PMID 20723236, 2010). "For assessment of the influence of CBX7 on PDAC tumor growth, PANC‐1 and ASPC‐1 cells were pre‐transfected with pCDH‐CBX7 and control plasmid." (PMID 40387566, 2025). "Mechanistically, DNMT1‐mediated suppression of CBX7 activates the extracellular signal‐regulated kinase (ERK) pathway through increased ERK phosphorylation, thereby facilitating tumor growth and progression." (PMID 40387566, 2025). "In summary, in hematopoiesis, CBX2, CBX7, and CBX8 have oncogenic roles, whereas CBX4 and CBX6 function as tumor suppressors." (PMID 38426219, 2024). "The most significant target genes were putative tumor oncogenes/promoters (TK1, KIF2C, UBE2C, AURKB) and potential tumor suppressors (CALCOCO1, CIRBP, KLHDC1, CBX7)." (PMID 36358602, 2022). "Then, we showed that CBX7 downregulated ETS1 to inactivate the tumor necrosis factor (TNF) signaling pathway, which inhibited tumor proliferation and enhanced the sensitivity of ccRCC cells to tyrosine kinase inhibitors (TKIs)." (PMID 35342353, 2022). "Additionally, targeting the epigenetic machinery has been proven as an efficient anti-cancer strategy in several tumor types, albeit it remains an open question whether Cbx3/HP1γ or Cbx7 epigenetic factors could become novel therapeutic targets in stem cell-like tumors." (PMID 36361869, 2022). "Our study found that CBX7 overexpression reduced the protein levels of p-ERK1/2 and p-p38 in LUAD and LUSC cells and tumor tissues." (PMID 35646140, 2022). "Western blotting showed that CBX7 overexpression significantly restrained the protein expression of p-ERK1/2 and p-p38 in tumor tissues in comparison to the lenti-NC (p < 0.01)." (PMID 35646140, 2022). "The remaining 3 genes (CBX7, TOP2A and BIRC5) filled the gaps of tumour cell regulation in stem cell, epigenetic, genomic instability, proliferation and differentiation." (PMID 35326543, 2022). "As the tumor progressed, patients with more advanced tumor grades tended to express higher mRNA expression of CBX3 and CBX4 but lower mRNA expression of CBX1, CBX5, CBX6, and CBX7." (PMID 34395271, 2021). "CBX7 inhibits YAP/TAZ, down-regulates CTGF (adverse prognostic product of tumor) with PRC2 as a member of PRC1, and reduces the phosphorylation level of c-Jun NH2-terminal kinase (JNK)." (PMID 34659360, 2021). "In agreement with patient tumor data, silencing of CBX2 and CBX7 showed opposite effects on all six measured end‐points." (PMID 33400401, 2021). "Consistently, we demonstrated that CBX7 was generally expressed in normal human urothelial tissues, but frequently silenced in UBC cell lines and primary tumor tissues due to promoter hypermethylation." (PMID 34035231, 2021). "Among genes upregulated in this group, CBX7, MIA3 and KANK1 have been shown to have tumor suppressive activities including roles in inhibition of cellular motility/migration and/or proliferation, and induction of cell cycle arrest in various malignancies." (PMID 32310997, 2020). "The chromobox protein homolog 7 (CBX7), one member of the polycomb group family, has been characterized mainly to play a tumor-suppressive role in human malignant neoplasias." (PMID 31709304, 2019).
tumor (continued). "Cbx7, one of the core components of Cbx-PRC1, and Ezh2 can be a proto-oncogene or a tumor suppressor in a context-dependent manner." (PMID 29802243, 2018). "Immunohistochemical evaluation indicated that CBX7 was significantly downregulated in PDAC tissues, compared with adjacent non-tumor tissues." (PMID 28030829, 2017). "Recently, we have reported that CBX7 regulates several genes involved in tumor progression such as E cadherin, cyclin E, SPP1 likely accounting for the critical role of CBX7 in carcinogenesis." (PMID 28259135, 2017). "Indeed, a drastic downregulation of CBX7 expression has been described in thyroid, pancreatic, colon, lung, gastric, bladder, breast carcinomas, and a more advanced stage of neoplastic disease and a poor survival has been directly correlated to the loss of CBX7 expression." (PMID 28259135, 2017). "Both CBX7 and CBX8 have been reported to repress the INK4a/ARF tumor suppressor locus allowing normal cells to bypass senescence." (PMID 24260522, 2013). "Two of these, CBX7 and EGR1, have well-described tumor suppressor functions, and recently DOK4 family members (DOK1, DOK2, and DOK3) were identified as lung tumor suppressors." (PMID 21375733, 2011). "For example, TXNIP (thioredoxin-interacting protein), EGR1, CBX7, HOXA9 and FOXN3 (checkpoint repressor 1) have tumor suppressor functions and are targeted by the potentially oncogenic miRNA miR-93, miR-183, miR-181b, miR-182 and miR-7." (PMID 21375733, 2011). "Studies have shown that CBX7 negatively modulates PTEN/Akt signaling during pancreatic tumorigenesis by upregulating PTEN transcription, suggesting that the PTEN/Akt pathway mediates the tumor‐suppressive activity of CBX7." (PMID 40387566, 2025). "Liver-specific loss of miR-181ab1 inhibited primary liver tumour progression via up-regulating CBX7 expression, but tumour induction requires both hepatic and non-hepatic miR-181." (PMID 35867177, 2022). "On the other hand, the relation of Pc group of CBX members is rather tumor and protein specific, albeit for CBX7, is significantly negative in all tested tumor types." (PMID 36361869, 2022). "The expression of CBX7, a confirmed miR-181 target, was up-regulated in GKO compared to WT tumours." (PMID 35867177, 2022). "We confirmed that SETDB2 (HR: 0.773, 95%CI: 0.640–0.932), SGF29 (HR: 0.918, 95%CI: 0.860–0.979), PRDM16 (HR: 0.891, 95%CI: 0.807–0.983), CBX7 (HR: 0.906, 95%CI: 0.833–0.986), and ZCWPW2 (HR: 0.325, 95%CI: 0.117–0.901) were protective genes, and they were all downregulated in the tumor samples." (PMID 36263018, 2022). "The Chi-square results showed that, compared with cancer tissues, the expression levels of CBX7 and E-cad negative in adjacent non-tumor tissues were lower (P < 0.05) and that of VIM was higher." (PMID 33748425, 2021). "Our results are consistent with the tumor suppression effects of CBX6 and CBX7." (PMID 34395271, 2021). "Importantly, CBX7 overexpression in UBC cells inhibited tumorigenicity, whereas CBX7 depletion promoted the tumor development, indicating its tumor-suppressive role in UBC." (PMID 34035231, 2021). "CBX7 protein level was remarkably correlated with T stage (p < 0.001) and tumor grade (p = 0.002), but not related with other features, such as age and gender." (PMID 34035231, 2021). "CBX7 expression was correlated with tumor grade, metastasis, and TMN stage, but not with other clinicopathological factors, including patients' age, gender, pT, and pN." (PMID 28030829, 2017). "Furthermore, there was a clear inverse relationship between CBX7 and CBX8 (and to a minor extent CBX2) mRNA expression levels of tumor and normal samples in the TCGA tumor data set overexpressing miR-375." (PMID 27449098, 2016). "Thus, miR-181a/b1 upregulation via CBX7 inhibition in the tumour cells—rather than non-tumour cells within the tumour microenvironment (TME)—led to liver tumour progression." (PMID 39120319, 2024).
tumor (continued). "High CBX7 expression significantly associates with cancer stemness attenuation and CBX7HIGH expressing tumors are robustly depleted with markers of stem cells, regardless of the tested tumor type." (PMID 36361869, 2022). "In addition, CBX7 was not expressed in > 90% (11 of 12) of patients who had died of the tumor (median survival time: 40 months), but was not expressed in only 55% (11 of 20) of patients with no tumor specific death (median survival time: 75 months) (p = 0.03, Pearson Chi2 test, two-sided)." (PMID 27449098, 2016). "CCK8 assays revealed that CBX7 and IGF-1R overexpression significantly increased tumor cell proliferation, counteracting the negative impact of FOXC1 knockdown." (PMID 38413558, 2024). "CBX7-AAV treatment dramatically reduced the size of primary liver tumours by 96% compared with controls, i.e. GFP-AAV, in mice without an alteration in the number of tumours." (PMID 35867177, 2022).
cancer (75 papers, 2007 to 2025). A tumor composed of atypical neoplastic, often pleomorphic cells that invade other tissues. "CBX7 has been linked to the repression of tumor suppressor genes, contributing to cancer progression and poor prognosis." (PMID 40525903, 2025). "The first reported chromodomain inhibitors were designed to target CBX7, because the association of CBX7 with H3K27me3 was shown to promote proliferation of cancer cells." (PMID 40302984, 2025). "Loss of CBX7 is associated with highly malignant phenotypes and poor prognosis in cancer and promotes resistance to TKIs." (PMID 37622176, 2023). "Our results clearly demonstrate yet unrecognized association of high CBX3 and low CBX7 expression with cancer stem cell-like phenotype of solid tumors." (PMID 36361869, 2022). "CBX7 depletion promoted cancer cell aggressiveness, and associated with a significant increase in the expression of cancer stem cell markers." (PMID 36361869, 2022). "Among the genes in the ZNF132 node, CBX7 is implicated in cancer progression and EMT, PTPRN2 confers resistance to apoptosis, and NTRK3 is a receptor tyrosine kinase whose overactive kinase domain is implicated in growth and metastasis." (PMID 34797887, 2021). "CBX7 is the most characterized CBX protein in cancer-associated studies which plays a critical role in cancer progression." (PMID 29190923, 2017). "This establishes the fact that the loss of Cbx7 in GBM is potentially one of the mechanisms adopted by the cancer cell to increase CTGF levels and become more aggressive." (PMID 27291091, 2016). "In conclusion, the loss of CBX7 expression associated to HMGA1b over-expression contributes to the positive regulation of the SPP1 gene expression in cancer." (PMID 25595895, 2015). "The regulation of CBX7 is particularly interesting because CBX7 is implicated in senescence and cancer." (PMID 26416703, 2015). "In conclusion, our data demonstrate that the loss of CBX7 associated to the increase of HMGA1b during carcinogenesis would contribute to cancer progression through the transcriptional deregulation of the SPP1 expression." (PMID 25595895, 2015). "A strong association between the loss of CBX7 expression and a reduced survival was also observed in patients affected by pancreatic and colon carcinomas." (PMID 25595895, 2015). "In order to better understand the role of the loss of CBX7 gene expression in cancer progression our work aimed to identify the genes regulated by CBX7." (PMID 24865347, 2014). "It has been previously observed that the reduced CBX7 expression is associated with several human carcinomas, and the complete loss of its expression correlates with the most advanced stages of malignancies." (PMID 24865347, 2014). "Low expression of the CBX7 gene is associated with poor prognosis in most cancers." (PMID 36081495, 2022). "In contrast to high-stemness tumors, cancer with CBX7 upregulation exhibit a lower mutation burden." (PMID 36361869, 2022). "CBX7 is involved in the reading recognition of H3K27me3 with its special structure and causes gene silencing, therefore CBX7 may be used as a clinical cancer treatment target." (PMID 34659360, 2021). "Moreover, downregulation of CBX7 is associated with poor prognosis and aggressiveness in human cancers." (PMID 31709304, 2019). "Similarly, underexpression of CBX7 appears to be associated with widespread inter-genic DNA hypomethylation in cancer, an entirely novel insight." (PMID 26169266, 2015). "The ability of miR‐9 to downregulate CBX7 expression causing p16INK4a induction and senescence could therefore provide an explanation for the role of miR‐9 in cancer and aging." (PMID 26416703, 2015). "Interestingly, while several isoforms for CBX7 were reported, no studies investigated whether the divergent roles of CBX7 in different cancers could be caused by different CBX7 isoforms." (PMID 32415167, 2020).